CYP26A1 (cytochrome P450 family 26 subfamily A member 1)
Diseases named in the same sentence as CYP26A1 in open-access papers (continued):
Sharing a sentence is not in itself a finding about the gene and the disease.
microcephaly (3 papers, 2022 to 2025). A congenital or acquired developmental disorder in which the circumference of the head is smaller than normal for the person's age and sex. "In contrast, the addition of DEAB to dorsally cyp26a1 RNA injected embryos increased the incidence of microcephaly to 100% of the embryos, showing that most of the RA signaling activity required for normal head development is localized dorsally." (PMID 35372345, 2022). "Dorsal CYP26A1 overexpression induced microcephaly with high efficiency (80%), with the majority of the embryos exhibiting severe microcephaly (61.1%)." (PMID 35372345, 2022). "Surprisingly, our analysis based on RA signaling knockdown using biosynthesis inhibitors or CYP26A1 overexpression resulted in the induction of microcephaly by reduced RA." (PMID 35372345, 2022). "Ventral cyp26a1 RNA injections resulted in a distribution of head phenotypes similar to control embryos (13.9% very mild microcephaly)." (PMID 35372345, 2022). "To address the missing phenotype we must remind ourselves that the Gsc+/Cyp26A1 model is an acute RA deficiency at early gastrulation, not a chronic or repeated acute PAE exposure as seen in studies which show microcephaly as a PAE phenotype." (PMID 37397253, 2023). "Our results of systemic RA reduction by CYP26A1 overexpression or the use of RA biosynthesis inhibition (DEAB) show that this signal is required for normal head development and its reduction results in microcephaly." (PMID 35372345, 2022). "Our Gsc+/Cyp26A1 mouse model recapitulates nearly all PAE phenotypes, yet there is one common finding in Xenopus and mouse PAE models, microcephaly, which we have not seen in our genetic model." (PMID 37397253, 2023).
ovarian carcinoma (3 papers, 2015 to 2023). A malignant neoplasm originating from the surface ovarian epithelium. "Consistent with this, significant high CYP26A1 protein expression was displayed in primary ovarian cancers, along with intense expression in metastatic ones." (PMID 38001897, 2023). "Researchers found that some CYP450 genes (e.g., CYP26A1) in primary ovarian cancer have significantly higher expressions compared with normal ovarian tissues." (PMID 25839051, 2015). "Previous studies demonstrated that an increased expression of CYP26A1 was found in human familial adenomatous polyposis adenomas, sporadic colon cancers, and primary ovarian cancer." (PMID 25839051, 2015). "Importantly, comparable levels of CYP26A1 mRNA were found in ovarian cancers." (PMID 38001897, 2023). "It has been reported that CYP26A1, MTRNR2L1, ELOA, and FAM53A were all related with ovarian carcinomas, and CYP26A1 may acts as a meiosis-inhibiting factor and related with the gonadal retinoic acid-degradation." (PMID 32425983, 2020).
acute promyelocytic leukemia (2 papers, 2015 to 2020). An aggressive form of acute myeloid leukemia (AML), characterized by arrest of leukocyte differentiation at the promyelocyte stage, due to a specific chromosomal translocation t(15;17) in myeloid cells. "In breast epithelial adenocarcinoma tissue cultures, head and neck squamous cell carcinoma cells, and acute promyelocytic leukemia (acute promyelocytic leukemia) cells, an increased expression of CYP26A1 and increased catabolic activity of RA can be detected." (PMID 25839051, 2015).
adenoma (2 papers, 2017 to 2024). A neoplasm arising from the epithelium. "In addition to the higher CYP26A1 expression and the consequential AtRA resistance, as CRC progresses, RAR β was downregulated in mice bearing mutations in the Apc tumor suppressor gene (ApcMIN mouse), human FAP adenomas, and human sporadic colon carcinomas." (PMID 28408791, 2017).
Hepatic fibrosis (2 papers, 2022 to 2023). The presence of excessive fibrous connective tissue in the liver. "In addition, CYP26A1-transfected cells showed changes in gene expression related to Hepatic Fibrosis and Adipogenesis, Cell Cycle, and others, including genes related to nervous system diseases, Cancer, and Developmental Disease, in NROB1-transfected cells." (PMID 36231133, 2022).
lung carcinoma (2 papers, 2005 to 2015). "However, both RARβ2 and CYP26A1 expression levels in treated MDA-MB-231 cells were relatively low compared to the levels seen in RA-sensitive lung cancer-positive control cells, Calu-6, also treated with 10 μM aRA for 3 days." (PMID 16012519, 2005). "However, RGS16, RARβ2, and CYP26A1 were not detectable and not RA inducible in both of the RA-resistant breast and lung cancer cells." (PMID 16012519, 2005).
spina bifida (2 papers, 2019 to 2021). A congenital neural tube defect in which vertebrae are not fully formed. "In humans, the loss of CYP26A1 function may be related to spina bifida." (PMID 34712245, 2021).
vitamin A deficiency (2 papers, 2011 to 2019). Deficiency of vitamin A due to malnutrition, malabsorption, or dietary lack. "It is therefore possible that products, such as retinoic acid, would have a role in the progression of HCC since a previous study revealed that vitamin A deficiency, which could result from a CYP26A1 depletion, is associated with increased susceptibility to carcinogenesis." (PMID 31258835, 2019).
acute coronary syndrome (1 paper, 2018). Signs and symptoms related to acute ischemia of the myocardium secondary to coronary artery disease. "A nominally significant SNP‐treatment interaction was found for CYP26A1 and acute coronary syndrome and symptom‐driven revascularization." (PMID 30371334, 2018). "There was a greater risk for acute coronary syndrome (odds ratio 1.85, 95% confidence interval 1.16‐2.77, P=0.02) and revascularization events (odds ratio 1.64, 95% confidence interval 1.2‐2.22, P=0.002) in major allele carriers at the CYP26A1 locus in the placebo group not seen in the niacin group." (PMID 30371334, 2018).
alopecia (1 paper, 2022). Hair loss usually from the scalp. "Although the exact mechanism of azole-mediated hair loss is unclear, voriconazole and itraconazole have been found to inhibit CYP26A1-mediated hydroxylation of retinoic acid in vitro at concentrations of >1 μM, with alopecia reported due to itraconazole, voriconazole, and posaconazole." (PMID 35448593, 2022).
anencephaly (1 paper, 2023). A rare neural tube defect during pregnancy, resulting in the absence of a large portion of the brain and skull in the fetus. "Gene expression studies have also revealed a connection between excess RA and NTDs in humans, including increased RAR transcription in human anencephaly samples and frameshift mutations in CYP26A1 linked to NTD induction." (PMID 38116205, 2023).
Barrett adenocarcinoma (1 paper, 2018). An adenocarcinoma arising from Barrett metaplastic epithelium in the esophagus. "CYP26A1 is elevated in Barrett’s adenocarcinoma, and can cause proliferation of epithelial cells when overexpressed." (PMID 29967615, 2018).
Blindness (1 paper, 2025). Blindness is the condition of lacking visual perception defined as a profound reduction in visual perception. "Interestingly, deletions involving the 5' portion of the EXOC6A gene and two adjacent cytochrome p450 genes (CYP26A1 and CYP26C1) are associated with autosomal-dominant nonsyndromic optic aplasia (ONA), an extremely rare disorder that causes unilateral or bilateral blindness in the affected eye." (PMID 40777261, 2025).
caudal regression syndrome (1 paper, 2016). "Mutations in CYP26A1 causes keratomalacia and caudal regression syndrome." (PMID 27367670, 2016).
cervical (1 paper, 2014). "We performed a semi-quantitative analysis of CYP26A1 expression in normal cervical epithelium and cervical intraepithelial neoplastic lesions by evaluating the area of positive signals per unit area of the entire tissue section." (PMID 25294402, 2014).
cervical cancer (1 paper, 2014). A primary or metastatic malignant neoplasm involving the cervix. "In addition, the association between CYP26A1 expression and a number of clinicopathological factors was also evaluated for both cervical carcinoma and HNC." (PMID 25294402, 2014).
cervical intraepithelial neoplasia (1 paper, 2014). "CYP26A1 positive signals were observed in cervical dysplasia, and the epithelium with dysplastic changes demonstrated more positive areas and signals." (PMID 25294402, 2014). "We first examined the expression and distribution of CYP26A1 in cervical intraepithelial neoplasia." (PMID 25294402, 2014).
colitis (1 paper, 2022). Inflammation of the colon. "In the liver, colitis reduced the mRNA levels of Aldh1a1, Cyp26a1, and Cyp26b1, suggesting reduced production as well as oxidation." (PMID 35889745, 2022).
Colorectal tumor (1 paper, 2017). "Colorectal tumor cells appear to lose the ability to produce AtRA while, at the same time, they appear to increase AtRA degradation via the cytochrome P450 enzyme (CYP26A1), a major retinoic acid catabolic enzyme." (PMID 28408791, 2017).
craniosynostosis (1 paper, 2025). Craniosynostosis is defined as the premature fusion of one or more cranial sutures leading to secondary distortion of skull shape resulting in skull deformities with a variable presentation. "Moreover, mutations in the Cyp26(a1,b1,c1) genes manifest in human patients by calvarial mineralization defects, craniosynostosis, hypertelorism, and learning disabilities, clinical features within the neuro-skeletal systems resembling the phenotype of patients with MN1 deletions." (PMID 40424121, 2025).
dermatitis (1 paper, 2013). An inflammatory process affecting the skin. "Accordingly, we found that expression of genes encoding RA degradation enzymes, cytochrome P450 26a1 (Cyp26a1; eight-fold induction) and Cyp26b1 (two-fold increase) was increased in allergen-induced dermatitis." (PMID 23977003, 2013).
dysplasia (1 paper, 2014). A usually neoplastic transformation of the cell, associated with altered architectural tissue patterns. "CYP26A1 was strongly expressed in all HSIL samples (n = 38), particularly in dysplasia with atypical cells occupying more than two-third of the epithelium thickness." (PMID 25294402, 2014).
embryonic carcinoma (1 paper, 2009). "We previously demonstrated in a mouse embryonic carcinoma cell model that anendogenous dominant negative RARα mutant, lacking part of the E domainharboring the RA-binding domain, induced concerted epigenetic repression of bothRARβ2 and CYP26A1, encoding for aRA hydrolase involved in RA catabolism." (PMID 19173001, 2009).
emphysema (1 paper, 2021). "For example, patients with emphysema have increased levels of CYP26A1 (an enzyme that degrades retinoic acid) in the endothelium." (PMID 34356894, 2021).
Hyperglycemia (1 paper, 2023). An increased concentration of glucose in the blood. "Taken together, findings in this paper support that hyperglycemia is a critical factor that leads to increased susceptibility to various malformations via down-regulation of Cyp26a1 and disruption of RA homeostasis." (PMID 37616226, 2023). "The present study, therefore, investigated the effect of hyperglycemia on Cyp26a1 expression in embryos and how it disrupted RA catabolism." (PMID 37616226, 2023). "Hence, we propose that hyperglycemia is a key factor that down-regulates Cyp26a1 expression in diabetic pregnancy." (PMID 37616226, 2023).
Kaufman Oculocerebrofacial Syndrome (1 paper, 2020). "Finally, deletions of CYP26A1 (MIM 602239) and CYP26C1 (MIM 608428) have previously been implicated in both nonsyndromic bilateral and unilateral optic nerve aplasia, and mutations in UBE3B (MIM 608047) have been described in Kaufman Oculocerebrofacial Syndrome (MIM 244450)." (PMID 32040484, 2020).
keratinization disorder (1 paper, 2021). "In this study, we establish a preclinical assessment of the pharmacological and toxicological properties of recently discovered dual CYP26A1/B1‐selective inhibitor, DX308, as a potential topical treatment for keratinization disorders and other retinoid‐responsive dermatological disorders." (PMID 35664983, 2021).
leiomyoma (1 paper, 2008). A well-circumscribed benign smooth muscle neoplasm characterized by the presence of spindle cells with cigar-shaped nuclei, interlacing fascicles, and a whorled pattern. "At lower concentrations of ATRA (10−8m and 10−7m), CYP26A1 was down-regulated two to fourfold in leiomyoma cells compared with myometrial cells." (PMID 18248652, 2008). "Significant up-regulation of CYP26A1 in myometrial cells and down-regulation in leiomyoma cells resulted in approximate equal levels of CYP26A1 in these cells at 10−6m ATRA concentration." (PMID 18248652, 2008). "Given the increased activity of metabolizing enzyme CYP26A1 in leiomyoma cells, we expected that there would be greater metabolism of active ATRA compound, thus negating the retinoid effect." (PMID 18248652, 2008). "In contrast, slight down-regulation of CYP26A1 was observed in ATRA exposed leiomyoma cells when compared to unexposed control cells." (PMID 18248652, 2008).
malocclusions (1 paper, 2023). "Of those 11 length measurements, Gsc+/Cyp26A1 mice have a significantly larger upper incisor height (p < 0.001), as expected compared to WT littermate mice, due to the pre-maxillary twisting causing malocclusion." (PMID 37397253, 2023). "We observed craniofacial malocclusions in 11 of 88 Gsc+/Cyp26A1 mice, a significant result when compared to WT littermates (12.5% frequency; p < 0.001)." (PMID 37397253, 2023).
metastatic colorectal cancer (1 paper, 2014). "CYP26A1, CYP26B1 and LRAT all showed immunoreactivity in both normal colonic epithelium and primary and metastatic colorectal cancer and in each case immunostaining was localised to the cytoplasm of cells." (PMID 24608339, 2014).
optic nerve hypoplasia (1 paper, 2013). "Phenotypic variability also was noted for carriers of CYP26A1, CYP26C1 and EXOC6A deletions within one family, ranging from normal vision, to uni- and bilateral optic nerve hypoplasia and variable levels of cognitive functioning (normal to impaired)." (PMID 23837398, 2013).
oral disorders (1 paper, 2015). "This is the first study to indicate that the mRNA expression of CYP26 families (CYP26A1 and CYP26B1) and their SNP variants play a novel role in the occurrence or developmental mechanism of malignant oral disorders." (PMID 25839051, 2015).
Pancreatic Carcinoma (1 paper, 2022). "However, the role of CYP26A1 in pancreatic cancer (PC) has not been explored." (PMID 35707714, 2022).
pharyngeal tumor (1 paper, 2020). "We found that the median (IQR) (median = 0.016; IQR = 0.003–0.105) expression of CYP26A1 mRNA in pharynx tumor tissues was found significantly lower than at oral tumor sites (median = 0.067; IQR = 0.019–0.254) (p = 0.036 < 0.05)." (PMID 33233443, 2020).
schizophrenia (1 paper, 2013). A major psychotic disorder characterized by abnormalities in the perception or expression of reality. "Seven genes were investigated and involved in the synthesis, degradation and transportation of RA, ALDH1A1, ALDH1A2, ALDH1A3, CYP26A1, CYP26B1, CYP26C1 and Transthyretin (TTR), for their roles in the development of schizophrenia." (PMID 24564241, 2013).
sirenomelia (1 paper, 2012). Sirenomelia is a rare, genetic, developmental defect during embryogenesis disorder characterized by fusion of the lower limbs and associated with some degree of lower extremity reduction and persistent vitelline artery. "Unfortunately, the low penetrance and early embryonic lethality of Bmp7;Tsg and of Cyp26a1 mutants exclude them as suitable models of human sirenomelia." (PMID 23028704, 2012). "This has been confirmed by the occasional presentation of sirenomelia in the genetic disruption of Cyp26a1, an enzyme that degrades RA and in the disruption of other genes that interact with the Cyp26 family of enzymes." (PMID 23028704, 2012).
skin cancer (1 paper, 2015). "A previous report indicated that, in long term sunlight-damaged skin cells and in the increased expression of RA-metabolizing enzymes, CYP26A1 may cause a deficiency of vitamin A, which could potentially lead to the malignant transformation of keratinocytes in the early development of skin cancer." (PMID 25839051, 2015).
squamous intraepithelial lesions (1 paper, 2014). "We determined CYP26A1 expression in non-neoplastic (normal) cervical epithelium, precancerous cervical dysplastic lesions, including low- and high-grade squamous intraepithelial lesions (LSIL and HSIL, respectively), and SCC." (PMID 25294402, 2014).